HIF1A (hypoxia inducible factor 1 subunit alpha)
Diseases named in the same sentence as HIF1A in open-access papers (continued):
Sharing a sentence is not in itself a finding about the gene and the disease.
cancer (continued). "Interestingly, co-transfection of HIF-1α or HIF-2α with full-length MAML1 into cancer cells induced ICN3-mediated Notch signaling dramatically, indicating a strong synergy between HIF factors and MAML1 in the activation of Notch pathway." (PMID 20010940, 2010). "Fourthly, THL could inhibit, in cancer cells, the expression of HIF-1α, a transcription factor that promotes metastasis by regulating the expression of metastasis-related genes." (PMID 20429953, 2010). "Interestingly, this work shows for the first time higher expression levels of two HIF-1α splice variants (HIF-1αTAG and HIF-1α736) in OR-negative carcinomas compared to normal/benign tissues." (PMID 20624301, 2010). "Cox regression univariate analysis revealed a significant effect of HIF-1α positivity on cancer-specific survival (log-rank test χ2=12.2, d.f.=1, HR=5.47 95% CI: 1.96–16.03, P<0.002) and disease-free survival (log-rank test χ2=10.85, d.f.=1, HR=4.47, 95% CI: 1.68–11.89, P=0.003)." (PMID 19436307, 2009). "Thus mechanisms that enhance HIF-1α expression are important in cancer development and would be potential targets for treatment." (PMID 19778456, 2009). "HIF-1α is overexpressed in many human cancers compared to normal tissues, and this overexpression is due to the interaction of a multiplicity of factors and pathways that reflect specific genetic alterations and extracellular stimuli (e.g., hypoxia) that impact on both synthesis and degradation." (PMID 19347037, 2009). "Ascorbic acid inhibits HIF-1α, through increasing resistibility to cancer." (PMID 19671184, 2009). "Among mitochondrial dysfunctions, impaired SDH activity in several cancer types has been associated to non-hypoxic HIF-1α stabilization, through a mechanism involving intracytoplasmic succinate accumulation and consequential PHD2 inhibition." (PMID 19587783, 2009). "Our meta-analysis does not strongly support the association between the HIF-1α 1790 G/A polymorphism and the cancer risk in other cancers." (PMID 20035632, 2009). "In addition, the oncogene MYC also plays a crucial role in hypoxic response, and cooperates with HIF-1α to alter cellular metabolism and promote cancer progression." (PMID 19948069, 2009). "Because the results from the sensitivity analysis were more valid, our meta-analysis does not strongly suggest the association between the HIF-1α 1790 G/A polymorphism and cancer risk in Caucasians." (PMID 20035632, 2009). "Normoxic expression of HIF-1α has been found in a number of cancer cell types." (PMID 19919690, 2009). "The overexpression of HIF-1α was found in various types of cancers of both human and mouse." (PMID 19893619, 2009). "Hence, we now provide evidence for another mechanism for impairing HIF-1α function in cancer cells by 2ME2-like inhibitors in terms of diminishing STAT3 activation." (PMID 18651980, 2008). "However, specific inhibitors to HIF-1α are still under development, thus demanding the evaluation of alternative strategies for inhibiting HIF-1α in cancers." (PMID 18651980, 2008). "Another possibility is that it is a robust marker of HIF-1α signalling, not specifically related to its function, the former being shown by several groups to be associated with poor outcome in this and other cancer types." (PMID 18542064, 2008). "The overall balance of the activation effects of HIF-1α may depend on the type of cancer and treatment modality used." (PMID 18847499, 2008). "Some studies have found that HIF-1α expression in head and neck, non-small cell lung and renal cell cancer is associated with an improved survival." (PMID 17179985, 2007). "First, functioning as an inducible binding partner of an important transcription factor regulating many genes involved in tumorigenesis and cancer progression, HIF-1α is an end downstream effector molecule common to the ERK-, Akt-, and STAT3-mediated signal transduction pathways." (PMID 17931419, 2007).
cancer (continued). "If such a hypothesis is true, it might be expected that infiltrative cancers would express higher levels of hypoxia inducible factor (HIF-1α), which in turn would upregulate a number of downstream mediators including various proteases, such as MMP2." (PMID 17353920, 2007). "Also, previous reports established that CXCR4 was up-regulated by hypoxia in monocytes, endothelial cells, and cancer cells by the stabilization and activation of HIF-1α protein." (PMID 17476338, 2007). "Therefore, we conclude that elevated HP in malignant tumors may facilitate the acquisition of 'stemness' characteristics of cancer cells by enhancing HIF-1α expression via β-catenin." (PMID 42224096, 2026). "To further assess downstream PARP1 signaling, we measured the expression of hypoxia-inducible factor 1 (Hif1a) and vascular endothelial growth factor alpha (Vegfa), both of which are involved in hypoxic and pro-angiogenic responses and are often dysregulated in cancer." (PMID 40869324, 2025). "Cancer cell-derived EVs carry key angiogenic factors, such as vascular endothelial growth factor, fibroblast growth factor, and hypoxia-inducible factor-1α (HIF-1α), which enhance endothelial cell proliferation and migration, leading to the formation of new blood vessels." (PMID 40574844, 2025). "However, Myc overexpressing cancer cells had superior effect on positively regulating multiple metabolic pathways including glycine, serine, threonine, glutamine, and nitrogen metabolism over Hif1α overexpression." (PMID 40050422, 2025). "Since a positive relationship between transcription factors HIF-1α and Nrf2 is often reported in experimental models of cancer cells grown under hypoxia, we evaluated whether the hypoxia-dependent accumulation of HIF-α was parallelled by enhanced expression of Nrf2 in both cell lines." (PMID 41103582, 2025). "In addition, HIF1α regulates metabolic reprogramming in cancer cells." (PMID 39953610, 2025). "The studies demonstrate hsa-miR-21-5p’s multifaceted role in angiogenesis and cancer progression, showing its ability to activate pro-angiogenic pathways via direct targeting of genes and indirect modulation of signaling pathways (e.g., through regulation of HIF1A)." (PMID 40362695, 2025). "Elevated levels of HIF-1α may therefore impact the development of other cancers." (PMID 40429943, 2025). "Lifestyle and environmental factors that influence HIF-1α activity, including oxidative stress and dietary interventions, may provide supplementary strategies to enhance reproductive outcomes while addressing cancer progression." (PMID 40136686, 2025). "Lastly, HIF-1α might also be involved in cancer resistance to chemo- and radiotherapies." (PMID 41514626, 2025). "However, decreased mRNA expression was observed for MLKL, STAT3, and HIF-1α in cancer cells." (PMID 41463386, 2025). "Supportively, the lactate transporter MCT4 and HIF1A, which are involved in promoting glycolysis and myofibroblast differentiation, were significantly upregulated, suggesting C3 cultures may be highly active in supporting cancer cell metabolism and growth." (PMID 41327318, 2025). "Low‐dose capecitabine may also reduce cancer stemness or selectively inhibit HIF‐1α." (PMID 40584409, 2025). "Thus, GATA3 stabilizes HIF1α to increase cancer cell invasiveness under hypoxia." (PMID 39942749, 2025). "Thus, HIF1α activation of ACSS2 allows cancer cells to use acetate lipid synthesis in hypoxic conditions when oxidative production of acetyl-CoA may be limited." (PMID 39284708, 2024). "Thus, ABCG1 may confer cell stemness and maintain stem‐like properties by enhancing aerobic glycolysis of malignant tumors through the HIF‐1a/PDK1 signaling axis." (PMID 38896016, 2024). "As HIF plays a key role in metabolism, we hypothesized that induction of HIF-1α or alterations in glycolytic metabolism may be the mechanism by which cancers regulate NKT cell responses, by either presenting activating or inhibitory lipid antigen in the context of CD1d." (PMID 39596374, 2024).
cancer (continued). "Therefore, the p-MYH9 /USP22/HIF-1α axis is critical for LR and cancer stemness." (PMID 39300073, 2024). "Moreover, HIF-1α regulates the transcription of genes responsible for producing proteases that alter or break down the extracellular matrix, thereby promoting the invasion of cancer cells." (PMID 38399410, 2024). "Noteworthy, by using GBM organoid model, the adaptation of cancer cells to harsh environment has been linked to the activation of the alternative RNA splicing events, such as asparagine endopeptidase (AEP) specifically cleaved DDX3X mediated by HIF-1α signaling." (PMID 39003252, 2024). "Therefore, the development of specific inhibitors to attenuate advanced autophagy processes mediated by ERK and Akt, consequently quelling the expression of autophagy-related genes, presents a promising avenue for combating drug-resistant cancers influenced by HIF-1α-induced autophagy." (PMID 38339408, 2024). "This approach, combined with the potential of combination therapies involving CDK and HSP-90 inhibitors, could significantly impact cancer progression and drug resistance by stabilizing HIF1α, suggesting a synergistic mechanism that broadens the scope of combating therapy resistance." (PMID 39697237, 2024). "Therefore, HIF-1α inhibitors may be a potential strategy for treating cancers resulting from PDLIM2 downregulation." (PMID 38880883, 2024). "Thus, these peptide-protein interactions could potentially be addressed by using peptide-based inhibitors for the HIF-1α-dependent cancers." (PMID 39493156, 2024). "Therefore, exploring a combined drug strategy of inhibiting EZH2 and HIF-1α together could potentially improve the effectiveness of cancer treatment." (PMID 38911968, 2024). "Cancer therapy may involve targeting HIF-1α or its metabolic pathways." (PMID 39099978, 2024). "Similarly, in HCC, elevated NRF2 and HIF-1α levels contribute to cancer growth and progression." (PMID 38424190, 2024). "Thus, a positive feedback loop would be established between MUC1 and HIF-1α that may serve as a global metabolic regulator in cancer cells." (PMID 38540735, 2024). "Based on the evidence that HIF-1α inhibition promotes NK cell function, permanently inhibiting HIF-1α expression in NK cells could be a useful cancer immunotherapy modality compared to transiently inhibiting HIF-1α using drugs such as the small-molecular compound KC7F2." (PMID 38892084, 2024). "Interestingly, nuclear PKM2 also functions as a coactivator for several transcription factors, such as HIF-1α or Oct4, by which regulates metabolic gene transcription and promotes tumorigenesis or sustains cancer stem cell (CSC) populations." (PMID 39728923, 2024). "Also, it has been observed that HIF-1α levels are correlated with aggressive cancer characteristics, indicating that HIF-1α may be a target for cancer treatment." (PMID 38801618, 2024). "Besides, E3 ligases have been implicated in modulating HIF1α stability in cancer independent of oxygen." (PMID 38769340, 2024). "Recently, it has been identified that hypoxia-inducible factor-1 alpha (HIF-1α) is a major transcriptional regulatory factor that responds to hypoxic environments and modulates the expression of many genes in the organism and is closely associated with the biological behavior of malignant tumors." (PMID 37588219, 2024). "Finally, HIF-1α promotes Snail levels to induce EMT in cancer invasion and metastasis." (PMID 39014491, 2024). "SIRT3 participates in reprogramming of cancer cell metabolism by activating the ROS/HIF-1α pathway: SIRT3-mediated decrease in ROS level induces activation of oxygen-dependent prolyl hydroxylases (PHD) with subsequent degradation of hypoxia-induced factor 1-α (HIF-1α)." (PMID 37175631, 2023). "Thus, overexpression of HIF-1α can induce increased mortality in many common cancers." (PMID 37266156, 2023).
cancer (continued). "In addition, a therapy aimed at restoring the levels of MUL1 in those cancers may downregulate Akt2 and HIF-1α and achieve tumor regression, as seen in other models." (PMID 38139010, 2023). "In addition, oxidative stress enhances HIF-1α expression and allows cancer cell adaptation." (PMID 36670988, 2023). "Indeed, such behaviors of cancer cells are controlled by HIF-1α." (PMID 37777750, 2023). "HIF-1α- and NPM1-regulated genes significantly overlapped and disruption of the HIF-1/NPM1 association with cell penetrating peptides derived from the ETD sequence of HIF-1α inhibited cancer cell proliferation and survival under hypoxia by triggering apoptosis." (PMID 36899934, 2023). "The treatment with NTG decreases the rates of immunoreactive cells for HIF-1α protein and the level of VEGF (vascular endothelial growth factor) protein was closely associated with HIF-1α and P-gp (P-glycoprotein) protein levels in cancer tissues after operation." (PMID 37173331, 2023). "As a result, HIF1α may promote miR-183/96/182 cluster expression, out of which miR-183 can also target VHL mRNAs to further inhibit its expression and constitutively promote HIF1α expression and associated cancer progression in a feedback loop mechanism." (PMID 37583933, 2023). "Besides, by controlling various CRLs, RBX1-mediated neddylation controls the degradation of several critical substrates including p21, p27, CDT1, hypoxia-inducible factor 1-alpha (HIF1α), and NRF2, which are closely associated with cancer progression or inhibition." (PMID 37717015, 2023). "Since HIF-1α is involved in hypoxia-induced senescence by activating cyclin-dependent kinase inhibitors p21CIP1 and p27KIP1 or inhibiting M-phase inducer CDC25A, anti-HIF-1α strategies may increase the action of anti-cancer agents by abating the senescent phenotype." (PMID 36846589, 2023). "Interestingly, the previous research proved that NECAB3 could activate hypoxia-inducible factor-1 alpha (HIF-1α) in cancer cells." (PMID 37215053, 2023). "HIF1A expression is mediated by hypoxia, and studies have found not only that this gene is overexpressed in many human cancers, but also that increased expression may relate to treatment failure and increased mortality in cancer patients." (PMID 36831404, 2023). "At the same time, the degradation of HIF-1α is inhibited during hypoxia, which leads to its continuous accumulation, which makes cancer cells adapt to a hypoxic environment and provides conditions for the proliferation, invasion, and metastasis of cancer cells." (PMID 36600313, 2023). "Furthermore, HIF-1α expression is still a major marker for detecting cancer neovascularization." (PMID 37964867, 2023). "Interestingly, it was unexpectedly found that when HIF1α was knocked down, calcified cancer cells could still produce calcification, but their proliferation and invasive ability were significantly decreased." (PMID 37957150, 2023). "Therefore, HIF-1α is a promising therapeutic target for cancer therapy." (PMID 37615898, 2023). "In general, the body of knowledge acquired in a century of research on cancer and immune metabolism has been overlooked in the interpretation of the data concerning several aspects of cellular glucose metabolism in DM, including aerobic glycolysis, HIF-1α induction, and PKM2 expression." (PMID 37305566, 2023). "Therefore, targeting HIF-1α/cisplatin in combination with HIF-1α inhibitors or degraders could provide a new opportunity for the treatment of individuals with platinum-resistant cancers." (PMID 38090580, 2023). "Moreover, MDA‐MB‐231 cells grown in FN‐silk networks had high cancer stem cell markers (i.e., NANOG, OCT4, and SOX2), accompanied by an up‐regulation of genes associated with basement membrane degradation and invasiveness (i.e., HIF1α, ITGAV, and MMP14)." (PMID 37693069, 2023). "Therefore, targeting HIF-1α has been an attractive strategy in cancer treatment." (PMID 36831463, 2023).
cancer (continued). "In this mini-review, we present the state-of-the-art on the role of the Warburg effect, HIF-1α, and PKM2 in cancer, inflammation, and DM to encourage multidisciplinary research to advance fundamental understanding in biology and pathways implicated in the link between DM and cancer." (PMID 37305566, 2023). "Moreover, the authors speculate that SESN2-mediated suppression of HIF-1α accumulation and cancer cell migration could have resulted from AMPK activation." (PMID 37284849, 2023). "Interestingly, HIF1α (but not HIF2α) was found to be linked to genetic instability and inhibition of DNA repair in cancer models." (PMID 37330004, 2023). "Furthermore, Eno1 is modulated by HIF-1α in many cancer cells." (PMID 37125075, 2023). "In this regard, studying the modulatory effects of miRNAs and lncRNAs on those glycolytic proteins linked with cancer progression, e.g., HK1, GAPDH, PKM2, GLUT1, GLUT3, HIF-1α, CAV1, Ras, HK2, LDHA, PGI/AMF, and PFKFB3, might be very favorable for the design of novel treatments for PC." (PMID 36332600, 2023). "Therefore, targeting HIF-1α has now become the main focus of drug development for cancer treatment." (PMID 37239383, 2023). "In addition, hypoxia-inducible factor 1-alpha (HIF-1α) may affect L-arginine metabolism in MDSCs, by inducing iNOS and Arg1 and enhancing the suppressive function of MDSCs in cancer patients." (PMID 36980527, 2023). "Therefore, pharmacological AsA concentrations might inhibit HIF-1α and suppress cancer cell proliferation while preventing IP progression." (PMID 38012636, 2023). "Thus, elevated interstitial fluid hydrostatic pressure in malignant tumours may promote the onset of the metastatic cascade by stabilizing HIF‐1α." (PMID 36701089, 2023). "It is thus tempting to speculate that ammonia produced by MAOA may enter a recycling process to promote growth in PC as well, which is a likely mechanism given that HIF1α can be stabilized by ammonia in cancer and appears to be a well-conserved effector in ammonia stress." (PMID 36860320, 2023). "Furthermore, Celastrol (tripterine) (SL.4) is another phytochemical, isolated from the root extracts of Tripterygium wilfordii (Thunder god vine) and Celastrus regelii, used to improve apoptosis of cancer cells by targeting HIF-1α and inhibit HIF-1α mediated angiogenesis and metastasis." (PMID 36014432, 2022). "Therefore, HIF1a would be involved in the energetic metabolism of cancers." (PMID 35053598, 2022). "Thus, HIF-1α has gradually become a potential target in the treatment of cancer." (PMID 35396948, 2022). "In addition, HIF-1α overexpression contributes to glycolysis promotion of cancer." (PMID 35712504, 2022). "In this context, it is also thinkable that the hypoxia/HIF-1α-linked increase of FAM57A transcript levels observed in our study may contribute to their relative elevation in cancers, since cancers are typically more hypoxic and often exhibit higher HIF-1α levels than corresponding normal tissues." (PMID 36291175, 2022). "However, HIF expression could differ according to cancer histotype: significant differences in the expression of HIF-1α were evident between the two types of EAOC (CCC and EnOC) and their coexisting AE and non-AE." (PMID 35457244, 2022). "This means that to inhibit cancer growth, it may be necessary to target both HIF-1α and HIF-2α." (PMID 36457492, 2022). "The response of cancer cells to hypoxia is principally ascribed to its transcriptional factors HIFs which includes three members, and they are heterodimers composed of an O2 sensitive α subunits (HIF-1α,or HIF-2α,or HIF-3α) and an O2 insensitive HIF-1β subunit." (PMID 36226050, 2022).